SNORD51 (small nucleolar RNA, C/D box 51)
Synonyms: U51; RNU51
Gene: Small nucleolar RNA gene on chromosome 2 (206,161,878 to 206,161,957, forward strand). Ensembl gene ENSG00000207047.
Gene Ontology:
Biological process: RNA processing
Cellular component: nucleolus
Homologues: Orthologues: macaque SNORD51 (96% identical), pig SNORD51 (90% identical), rabbit SNORD51 (89% identical), guinea pig SNORD51 (88% identical), mouse Gm26457 (88% identical), rat Snord51 (88% identical).
Diseases named in the same sentence as SNORD51 in open-access papers:
SNORD51 is named in the same sentence as 3 diseases in open-access papers, as found by Europe PMC text mining. Sharing a sentence is not in itself a finding about the gene and the disease. The quoted sentences say what the papers report.
glioblastoma (1 paper, 2024). The most malignant astrocytic tumor (WHO grade IV). "We mainly verified the regulatory effects of KHDRBS1, SNORD51 and ZBED6 on pentose phosphate pathway and malignant biological behavior in glioblastoma cells, such as proliferation, migration and invasion." (PMID 39516455, 2024).
tumor (1 paper, 2024). "Finally, our in vivo study showed that the combination of KHDRBS1 knockdown, SNORD51 knockdown and ZBED6 overexpression significantly reduced the volume of the xenograft GBM tumor and prolonged the survival time of nude mice." (PMID 39516455, 2024).
SNORD51 also shares sentences with these, for which no sentence is quoted: infection (1 paper).